BCL3 (BCL3 transcription coactivator)
Description:
Contributes to the regulation of transcriptional activation of NF-kappa-B target genes. In the cytoplasm, inhibits the nuclear translocation of the NF-kappa-B p50 subunit. In the nucleus, acts as transcriptional activator that promotes transcription of NF-kappa-B target genes. Contributes to the regulation of cell proliferation (By similarity).
Synonyms: BCL4; D19S37
Tractability: Small molecule: a high-quality ligand is known. PROTAC: UniProt records ubiquitination sites on it; ubiquitination databases record sites on it; its protein half-life has been measured; a small molecule that binds it is known.
Gene: Protein-coding gene on chromosome 19 (44,747,705 to 44,760,044, forward strand). Ensembl gene ENSG00000069399.
Subcellular location: Nucleus; Cytoplasm; Cytoplasm, perinuclear region
Subcellular location (Human Protein Atlas): Nucleoplasm; Basal body; Cytosol; Midbody; Primary cilium; Vesicles
Gene Ontology:
Molecular function: DNA-binding transcription factor binding; histone deacetylase binding; protein binding; protein-macromolecule adaptor activity; transcription corepressor activity; transcription coactivator activity; transcription coregulator activity
Biological process: canonical NF-kappaB signal transduction; DNA damage response; negative regulation of apoptotic process; negative regulation of DNA-templated transcription; negative regulation of interleukin-8 production; negative regulation of non-canonical NF-kappaB signal transduction; negative regulation of receptor signaling pathway via JAK-STAT; positive regulation of DNA-templated transcription; positive regulation of translation; protein import into nucleus; regulation of apoptotic process; regulation of non-canonical NF-kappaB signal transduction; response to UV-C; response to virus; negative regulation of cytokine production; positive regulation of gene expression; response to other organism; response to stress
Cellular component: Bcl3-Bcl10 complex; Bcl3/NF-kappaB2 complex; cytoplasm; nucleoplasm; nucleus; protein-containing complex; perinuclear region of cytoplasm
Genetic constraint (gnomAD): Loss-of-function variants: 11 observed, 25.94 expected, observed/expected ratio (o/e) 0.42, 90% interval 0.27 to 0.7. The synonymous counts are far from expectation, so gnomAD's model fits this gene poorly and the ratio says little. Missense variants: 558 observed, 500.09 expected, observed/expected ratio (o/e) 1.12, 90% interval 1.04 to 1.2. Synonymous variants: 307 observed, 229.19 expected, observed/expected ratio (o/e) 1.34, 90% interval 1.22 to 1.47.
Homologues: Orthologues: chimpanzee BCL3 (99% identical), macaque BCL3 (99% identical), dog BCL3 (90% identical), pig BCL3 (90% identical), mouse Bcl3 (81% identical), guinea pig BCL3 (76% identical), rabbit BCL3 (71% identical), rat Bcl3 (58% identical), zebrafish bcl3 (42% identical), tropical clawed frog bcl3 (40% identical). Paralogues in human: NFKBIE (26% identical), POTEB3 (19% identical), POTED (19% identical), POTEE (19% identical), POTEI (19% identical), POTEC (19% identical), POTEF (19% identical), POTEJ (19% identical), POTEB (19% identical), POTEB2 (19% identical), POTEG (18% identical), POTEH (18% identical), and 2 more.
Diseases named in the same sentence as BCL3 in open-access papers:
BCL3 is named in the same sentence as 171 diseases in open-access papers, as found by Europe PMC text mining. Sharing a sentence is not in itself a finding about the gene and the disease. The quoted sentences say what the papers report.
breast carcinoma (35 papers, 1999 to 2025). "Bcl3 is known to be overexpressed in human breast cancers and is associated with reduced metastasis-free survival." (PMID 38255248, 2024). "Strikingly, loss of Bcl-3 resulted in the attenuatedpulmonary metastasis of breast cancer, as measured by significantly reducednumbers of metastatic foci and decreased tumor burden." (PMID 27906182, 2016). "Melanoma, hepatocellular carcinoma, and breast cancer are instances where cyclin D1 expression is upregulated due to the BCL3-p50 or BCL3-p52 association." (PMID 22235375, 2011). "Bcl3 has been implicated with a role in tumour progression and is activated alongside NF-κB subunits p50 and p52 in breast cancer; however, Bcl3 knockout mice remain viable with minimal adverse effects and show increased apoptosis in mammary glands, making it an attractive therapeutic target." (PMID 38255248, 2024). "Although this was not investigated in this study, our previous work has shown that a loss of Bcl3 can regulate CDC42 transcription in breast cancer cell lines, including MCF-7 cells, which could also contribute to ROS production and senescence." (PMID 38255248, 2024). "Furthermore, in breast cancer Bcl-3 stabilizes CtBP1, causing a decrease in CtBP1-dependent pro-apoptotic genes p21 and NOXA." (PMID 39327470, 2024). "Bcl-3 is expressed in human breast cancers and is associated with poor prognosis." (PMID 35681213, 2022). "ROC analysis showed BCl3 gene was most specific with breast cancer-associated bone metastasis." (PMID 35388653, 2022). "Since Bcl-3 expression could be linked to unfavorable prognosis of breast cancer patients that received endocrine treatment, Bcl-3 may be a suitable biomarker for predicting endocrine therapy response of patients with ERα-/PR-positive breast cancers." (PMID 26515727, 2015). "We next sought to analyze whether Bcl-3 is associated with the outcome of breast cancer patients that suffered from ERα/PR-positive tumors and received endocrine treatment." (PMID 26515727, 2015). "Based on this analysis, the bcl3 promoter was selected as a model SP1-enriched promoter, as it exhibited a higher QGRS score and the bcl3 gene is strongly associated with breast cancer." (PMID 40884402, 2025). "In contrast BCL3 drives metastasis in ERBB2-driven mammary tumors, and its expression has been shown to correlate with poor survival in ER + breast cancer, including ILC." (PMID 40597443, 2025). "Recently, a small molecule targeting Bcl-3 demonstrated encouraging outcomes in breast cancer, effectively inhibiting tumor growth and metastasis." (PMID 39327470, 2024).
breast carcinoma (continued). "The anti-metastatic effects of Bcl3 suppression have been well documented; however, the consequences of suppressing Bcl3 on breast cancer viability, other than in response to DNA damage, remain poorly defined." (PMID 38255248, 2024). "The NF-κB co-factor Bcl3 is a proto-oncogene that promotes breast cancer proliferation, metastasis and therapeutic resistance, yet its role in breast cancer cell survival is unclear." (PMID 38255248, 2024). "Here, we sought to determine the effect of Bcl3 suppression alone on breast cancer cell viability, with a view to informing future studies that aim to target Bcl3 therapeutically." (PMID 38255248, 2024). "Pharmacological suppression of BCL3 in adult mice however led to a significant reduction in tumour volume in two xenograft models of breast cancer." (PMID 38195591, 2024). "High levels of Bcl-3 expression and activation have been detected in different types of human cancer, such as skin cancer, leukemia, hepatocellular carcinoma, breast cancer, colon cancer, ovarian cancer and prostate cancer." (PMID 38238702, 2024). "Despite the known role of Bcl3 in promoting breast cancer progression and metastasis, its role in regulating breast tumour cell survival without additional exogenous stress has remained unclear." (PMID 38255248, 2024). "Having established the importance of Bcl3/NF-κB function in maintaining cell viability in breast cancer cell lines, we next sought to determine the clinical relevance of Bcl3 expression in breast cancer." (PMID 38255248, 2024). "In conclusion, our findings establish Bcl3 as an important regulator of breast cancer cell survival, highlighting its regulation of the NF-κB signalling network as an important factor in maintaining survival." (PMID 38255248, 2024). "shRNA knockdown of BCL3 in breast cancer cells with concomitant TGF-β stimulation, revealed decreased SMAD3 phosphorylation, decreased SMAD3 protein levels and attenuated TGF-β reporter luciferase assay activity." (PMID 38195591, 2024). "This has important implications for predicting therapeutic responses to targeted Bcl3 inhibition in breast cancer." (PMID 38255248, 2024). "Bcl3 was suppressed by siRNA in breast cancer cell lines before changes in viability, proliferation, apoptosis and senescence were examined." (PMID 38255248, 2024). "Formaldehyde-fixed, paraffin-embedded samples of 180 breast cancer patients were analyzed for BCL3 expression by immunohistochemistry." (PMID 35020071, 2022). "Cell migration is largely mediated through Rho GTPase activity which is regulated by Cdc42 in a Bcl-3-dependent manner in breast cancer cell lines." (PMID 35681213, 2022). "The anti-apoptotic protein, Bcl-2, can be regulated by p52 homodimers in conjunction with its transactivation partner, Bcl-3, in both leukemic and breast cancer cells." (PMID 35681213, 2022). "Earlier studies already demonstrated that BCL3 is frequently overexpressed in breast cancer and mostly localized to the nucleus." (PMID 35020071, 2022). "As described, Bcl-3 can be detected in human breast cancers and breast cancer cell line xenograft tumors." (PMID 35681213, 2022). "During breast cancer pulmonary metastasis in mice, TGFβ signaling stabilizes Smad3 necessary for metastasis in a Bcl-3-dependent manner." (PMID 35681213, 2022). "We then stained paraffin-embedded tissue of our breast cancer cohort for BCL3 by immunohistochemistry." (PMID 35020071, 2022).
breast carcinoma (continued). "Involution stroma has been shown to promote the invasion of tumor cells resulting in metastatic disease, a function that is severely attenuated in bcl-3 null mouse mammary tumor cells." (PMID 35681213, 2022). "The role of Bcl-3 in tumorigenesis and tumor pathology was also assessed using a stochastic carcinogen-induced mammary tumor model." (PMID 35681213, 2022). "In breast cancer, cmvIL-10 was shown to directly promote growth and migration of breast cancer cells and upregulate proto-oncogene Bcl-3." (PMID 33808294, 2021). "For example, data have shown BCL-3 regulates apoptosis in colorectal and cervical tumour cell lines following UV-radiation and protects breast carcinoma cells from undergoing apoptosis following UV-radiation." (PMID 31930327, 2020). "Bcl3 is also involved in solid tumor progression like ovarian, cervical cancers, mammary cancer metastasis and tumor progression in breast cancer." (PMID 32659965, 2020). "Apart from hematology malignancies, BCL3 has been shown to be participated in progression of diverse solid tumors, such as breast cancer, renal-cell carcinoma, non-small-cell lung cancer, cervical cancer, colorectal cancer." (PMID 30357752, 2019). "Elevated expression of BCL3 acted as unfavorable prognostic indicator has been reported in chronic lymphocytic leukemia, non-Hodgkin’s lymphoma, colorectal cancer, breast cancer." (PMID 30357752, 2019). "Increased expression of Bcl-3 was observed in breast cancer, skin squamous cell carcinoma, endometrial cancer, nasopharyngeal cancer, and some lymphomas." (PMID 29874793, 2018). "We and others have reported that Bcl-3 mRNA and protein levels are increased in the tumor tissues compared with normal tissues in various types of cancer including colorectal cancers, breast cancers." (PMID 29228604, 2017). "We then evaluated the elevated expression of Bcl-3 with metastaticprogression and metastasis-free survival in breast cancer patients." (PMID 27906182, 2016). "Then weconsidered the protein level of Bcl-3 and Smad3 in some breast cancer cellswith different metastasis potential." (PMID 27906182, 2016). "Here we show that Bcl-3, a member of the IκBfamily, serves as a critical regulator in TGFβ signaling tomodulate breast cancer pulmonary metastasis." (PMID 27906182, 2016). "We found theelevated expression of Bcl-3 correlated with metastatic progression andmetastasis-free survival in breast cancer patients." (PMID 27906182, 2016). "Patientswith breast cancers (n=116, P=0.025) thatexpressed higher mRNA levels of Bcl-3 had a significantly lowermetastasis-free survival than patients whose tumors expressed lower levelsof Bcl-3." (PMID 27906182, 2016). "These findingsdemonstrate a clinical significance of Bcl-3 in breast cancer and raise theneed to further understand the function of Bcl-3 in breast tumormetastasis." (PMID 27906182, 2016). "The depletion of Bcl-3 in breast cancer cells reduced the steady-state levelsof Smad3 protein upon TGFβ stimulation but no change in theSmad3 mRNA level." (PMID 27906182, 2016). "Here we reportthat Bcl-3 functions as a critical regulator of TGFβ signaling bystabilizing Smad3 to promote the pulmonary metastasis of breast cancer." (PMID 27906182, 2016). "In our study, we found that Bcl-3 regulated breast cancerpulmonary metastasis in breast cancer cells by modulating TGFβsignaling via the stabilization of Smad3 and other metastasis-related proteinssuch as ID1 (see discussion below)." (PMID 27906182, 2016). "Bcl-3 expression was significantlyassociated with metastasis-free survival in breast cancer patients." (PMID 27906182, 2016).
breast carcinoma (continued). "CCND1 is frequently amplified/overexpressed in human cancers, and BCL3 is a candidate proto-oncogene whose function is reportedly required for metastasis of HER2-positive breast cancer cells." (PMID 27382434, 2016). "Elevated levels of BCL3 have been detected in a large number of cancers, including breast cancer, and it has been reported that BCL3 can have an anti-apoptotic effect in cancer." (PMID 26219963, 2015). "Initial reports showed that Bcl-3-p52 dimers are able to transactivate the antiapoptotic gene BCL2 in MCF7AZ breast cancer cells." (PMID 22195643, 2011). "Additional evidence comes from animal studies, in which it has been shown that overexpression of Bcl-3 is able to increase the establishment and growth of breast cancer xenografts." (PMID 22195643, 2011). "Based on the definition of CSCs role in tissue of origin and clonal expansion of solid tumours and their role in colonization of tumour cells during metastasis, the therapeutic effect of BCL3 inhibition on cancer stemness has also been described in breast cancer models)." (PMID 38195591, 2024). "Moreover, in describing a novel BCL3 inhibitor with anti-cancer properties in models of breast cancer, we have reported on the transcriptional responses of a panel of key NFkB-responsive genes to BCL3 inhibition mediated both by siRNA and pharmacologically." (PMID 38195591, 2024). "Thus, using a stochastic carcinogen-induced mammary tumour model in BCL3-knockout mice, BCL3 was shown to promote the formation of mammary adenocarcinomas through elevated NF-κB leading to the maturation of luminal progenitors." (PMID 38195591, 2024). "However, in our breast cancer cohort, nuclear localized BCL3 seemed more important for RFS than the cytosolically localized protein." (PMID 35020071, 2022). "Based on these data, a potential role for p52 and BCL3 in breast cancer was postulated." (PMID 35020071, 2022). "Bcl3 is aberrantly expressed in tumors, including breast cancer." (PMID 35388653, 2022). "Additionally, we were interested in the distribution of BCL3 mRNA abundance in a larger cohort of breast cancer cases." (PMID 35020071, 2022). "Excitingly, given the expression of BCL-3 in a wide range of cancers including breast cancer, these findings could translate into improving therapy response or stratifying treatment in other cancer types beside CRC." (PMID 35468497, 2022). "Bcl-3 has been shown to stabilize the transforming growth factor-β (TGFβ)-activated transcription factor, Smad3, in conjunction with metastatic spread of mouse mammary tumors." (PMID 35681213, 2022). "The Id proteins are also regulated through TGF-β signaling and similar to observations in the metastatic tumor model where Id3 was reduced in bcl-3−/− mammary tumors, bcl-3 null mammary glands were devoid of Id3 expression at involution, while expression was strongly increased in WT glands." (PMID 35681213, 2022).